LIG1 (DNA ligase 1)
Description:
DNA ligase that seals nicks in double-stranded during DNA repair. Also involved in DNA replication and DNA recombination.
Synonyms: LIGI; hLig1; IMD96
Tractability: Small molecule: a structure with a bound ligand is known; a high-quality ligand is known; it belongs to a druggable protein family. PROTAC: ubiquitination databases record sites on it; its protein half-life has been measured; a small molecule that binds it is known.
Target class: Enzyme; Ligase
Gene: Protein-coding gene on chromosome 19 (48,115,445 to 48,170,654, reverse strand). Ensembl gene ENSG00000105486.
Subcellular location: Nucleus
Subcellular location (Human Protein Atlas): Nucleoplasm; Golgi apparatus; Vesicles
Pathways (Reactome):
DNA Repair: Gap-filling DNA repair synthesis and ligation in GG-NER; Gap-filling DNA repair synthesis and ligation in TC-NER; HDR through Single Strand Annealing (SSA); PCNA-Dependent Long Patch Base Excision Repair; POLB-Dependent Long Patch Base Excision Repair
Cell Cycle: Processive synthesis on the C-strand of the telomere
DNA Replication: Processive synthesis on the lagging strand
Developmental Biology: Regulation of MITF-M-dependent genes involved in DNA replication, damage repair and senescence
Disease: Early Phase of HIV Life Cycle
Gene Ontology:
Molecular function: DNA ligase activity; protein binding; DNA binding; DNA ligase (ATP) activity; ATP binding
Biological process: base-excision repair; V(D)J recombination; anatomical structure morphogenesis; base-excision repair, gap-filling; DNA repair; lagging strand elongation; mismatch repair; Okazaki fragment processing involved in mitotic DNA replication; telomere maintenance via semi-conservative replication; DNA biosynthetic process; DNA recombination
Cellular component: nucleoplasm; nucleus
Genetic constraint (gnomAD): Loss-of-function variants: 66 observed, 112.25 expected, observed/expected ratio (o/e) 0.59, 90% interval 0.48 to 0.72. The upper end of that interval is the gene's LOEUF score, 0.72, which puts it in group 2 of 6, group 1 being the genes least tolerant of losing a copy. Missense variants: 1,080 observed, 1,193 expected, observed/expected ratio (o/e) 0.91, 90% interval 0.86 to 0.95. Synonymous variants: 470 observed, 483.72 expected, observed/expected ratio (o/e) 0.97, 90% interval 0.9 to 1.05.
Gene-disease validity (ClinGen):
ClinGen rates the evidence that LIG1 causes each of these diseases.
immunodeficiency 96 (autosomal recessive): Definitive. An autosomal recessive disorder characterized by onset of recurrent, usually viral, respiratory infections in infancy or early childhood.
Homologues: Orthologues: chimpanzee LIG1 (99% identical), macaque LIG1 (95% identical), dog LIG1 (87% identical), pig LIG1 (85% identical), mouse Lig1 (84% identical), rat Lig1 (83% identical), rabbit LIG1 (74% identical), tropical clawed frog lig1 (61% identical), zebrafish lig1 (60% identical), Drosophila melanogaster DNAlig1 (41% identical), Caenorhabditis elegans lig-1 (35% identical). Paralogues in human: LIG3 (22% identical), LIG4 (17% identical).
Diseases named in the same sentence as LIG1 in open-access papers:
LIG1 is named in the same sentence as 71 diseases in open-access papers, as found by Europe PMC text mining. Sharing a sentence is not in itself a finding about the gene and the disease. The quoted sentences say what the papers report.
Immunodeficiency (12 papers, 2011 to 2025). Failure of the immune system to protect the body adequately from infection, due to the absence or insufficiency of some component process or substance. "In comparison, our biochemical analyses of full-length and Δ232 truncated forms of LIG1 reveal the impact of K845N to be distinct from LIG1 alleles associated with immunodeficiency syndrome." (PMID 40791503, 2025). "Biallelic mutations in LIG1 located on chromosome 19 have been associated with LIG1 deficiency disease and patients exhibit hypogammaglobulinemia, lymphopenia, and immunodeficiency of variable severity." (PMID 39159820, 2024). "Subsequently, five more patients were identified with rare variants in the LIG1 gene, and these individuals also showed symptoms of immunodeficiency." (PMID 39510190, 2024). "This patient’s symptoms are consistent with the clinical description of LIG1 deficiency which includes immunodeficiency, dysmorphic features, and growth delay." (PMID 39510190, 2024). "Human immunodeficiency syndrome caused by the mutations in the LIG1 gene (P529L, R641L, and R771W) leads to an inherited LIG1 deficiency, which was established from the individuals that exhibit growth retardation, developmental delays, sun sensitivity, and severe immunodeficiency." (PMID 41346861, 2025). "LIG1, a DNA ligase essential for DNA maintenance and repair, is crucial for embryonic development, and mutations in LIG1 have been linked to immunodeficiency." (PMID 41200508, 2025). "Some biallelic missense mutations in LIG1 cause a recessive primary immune deficiency referred to as LIG1 Syndrome or IMD96 (MIM #619774) associated with reduced LIG1 catalytic activity and altered DNA binding, highlighting potential for specific amino acid substitutions to alter LIG1 function." (PMID 40791503, 2025). "Hypomorphic LIG1 variants R771W and R641L cause immune deficiencies in LIG1 Syndrome patients." (PMID 39510190, 2024). "In vitro these LIG1 variants have decreased catalytic efficiency and increased abortive ligation and it is not known if either biochemical defect is sufficient on its own to cause immune deficiency." (PMID 39510190, 2024). "However, individuals with biallelic hypomorphic LIG1 alleles suffer from symptoms of immune deficiency." (PMID 39510190, 2024). "LIG1 codes for a protein involved in joining of Okazaki fragments during DNA replication, and its mutation is associated with delayed growth, cancer and possibly immunodeficiency." (PMID 37026480, 2023). "Interestingly, biallelic LIG1 mutations were identified in 5 human subjects, these patients suffered from a spectrum of immune deficiencies characterized by lymphopenia, likely resulting from defective DNA repair in B cells and T cells." (PMID 32547565, 2020). "SNPs in gene LIG1 may cause DNA Ligase I deficiency which results in immunodeficiency and increased sensitivity to DNA-damaging agents." (PMID 22558535, 2011).
lung carcinoma (11 papers, 2016 to 2025). "A meta-analysis on the relationship between LIG1 gene polymorphisms and lung cancer risk suggested that the rs156641 polymorphism was significantly associated with lung cancer risk." (PMID 39234248, 2024). "In lung cancer research, it is believed that a polymorphism in exon 6 of the DNA ligase gene LIG1 may be associated with susceptibility to lung adenocarcinoma and squamous cell carcinoma." (PMID 39234248, 2024). "Polymorphic variants of LIG1 may influence lung cancer, upper GI cancers 20 and head & neck cancers." (PMID 34373746, 2021). "Many studies confirmed that variants in LIG1 may predispose to smoking‐related lung cancer." (PMID 32580248, 2020). "Significant associations with lung cancer and polymorphisms in genes involved in DNA damage sensing (ATM) and, in four genes encoding proteins involved in mismatch repair (LIG1, LIG3,MLH1, and MSH6) found." (PMID 40958859, 2025). "Early studies identified associations with lung cancer risk in selected mutated NER genes (ERCC1-6, LIG1, POLE, XPA, and XPC genes)." (PMID 30181806, 2018). "Despite their roles related to lung cancer, the kinases associated with the identified phosphorylation sites matching the CK2 phosphorylation motif, including serine 141 of LIG1, serines 263 and 252 of HSP90AA1 and serines 206, 28 and 34 of NCL, have not been reported." (PMID 28290473, 2017). "Single nucleotide polymorphisms (SNP) in genes, such as ALDH7A1, POLA2, LIG1, and ERCC6L, are important for the development of various cancers, such as esophageal squamous cell carcinoma, lung cancer, and oral cancer, but these polymorphic genes may be linked with pathogenesis of BRCA." (PMID 31311202, 2019).
Huntington disease (8 papers, 2020 to 2026). Huntington disease (HD) is a rare neurodegenerative disorder of the central nervous system characterized by unwanted choreatic movements, behavioral and psychiatric disturbances and dementia. "We examined a recently characterized minor variant of LIG1, K845N, which has a protective effect in Huntington's disease, and found that the fidelity of K845N LIG1 is also enhanced as free Mg2+ decreases." (PMID 41895445, 2026). "Huntington’s disease (HD)-associated mutation in the LIG1 gene, K845N, is associated with delayed symptom onset and predicted to suppress CAG repeat expansion." (PMID 41346861, 2025). "Re-analysis of Huntington’s disease AOO exome sequencing data showed that, in the early onset Huntington’s disease group, deleterious variants were enriched in FAN1 and depleted in LIG1, MSH3 and PMS1." (PMID 39801710, 2025). "LIG1 and RRM2B were both associated with neurofibrillary tangles, which may provide a link to a potential role in mHTT aggregates, while MSH3 was associated with several cortical morphology-related traits relevant to Huntington’s disease." (PMID 39801710, 2025). "When removing count-based terms, we visualized 11 signals from four Huntington’s disease modifier genes (MSH3 n = 8, LIG1 n = 1, MLH1 n = 1, RRM2B n = 1), some of which are related to neurological processes that could be relevant to Huntington’s disease." (PMID 39801710, 2025).
ovarian carcinoma (5 papers, 2021 to 2024). A malignant neoplasm originating from the surface ovarian epithelium. "In research on ovarian cancer, overexpression of LIG1 and LIG3 is associated with aggressive phenotypes, platinum resistance and lower progression-free survival (PFS)." (PMID 39234248, 2024). "Taken together, the data suggest that LIG1 specific inhibitor monotherapy or in combination with PARP inhibitor could be a novel synthetic lethality strategy in XRCC1 deficient ovarian cancers." (PMID 34373746, 2021). "Taken together, the data implies that LIG1 blockade by small molecule inhibitor could be a promising strategy in XRCC1 deficient or proficient ovarian cancers." (PMID 34373746, 2021). "Specifically, LIG1 is an attractive target for personalization of ovarian cancer therapy, and decreased eEF2 phosphorylation, mediated by increased PP2A activity, contributes to resistance to HER2 inhibition." (PMID 37519889, 2023). "LIG1 deletion in ovarian cancer (OC) cells increased platinum cytotoxicity, which was associated with the accumulation of DSBs, S-phase arrest and increased proportions of apoptotic cells." (PMID 38044421, 2023). "DNA ligase 1, also known as LIG1, has been singled out as a potentially fruitful therapeutic modification target for ovarian cancer." (PMID 35957812, 2022). "Given the independent significance of LIG1, we also conducted sub-group analysis in platinum sensitive and resistant ovarian cancer." (PMID 34373746, 2021). "Taken together, the pre-clinical and clinical data provides evidence that LIG1 is a predictor of response to platinum therapy in ovarian cancers." (PMID 34373746, 2021). "The data provides evidence that LIG1 depletion not only enhances platinum sensitivity but can also reverse platinum resistance in ovarian cancer cells." (PMID 34373746, 2021). "LIG1, LIG3 and LIG4 expression profiling in epithelial ovarian cancers: We initially evaluated LIG1, LIG3 and LIG4 expression at protein and transcriptional level in clinical cohorts of epithelial ovarian cancers." (PMID 34373746, 2021). "We have previously shown that XRCC1, a key scaffolding protein and a partner for LIG3 or LIG1 is a key predictor of platinum sensitivity in ovarian cancer." (PMID 34373746, 2021). "We evaluated the clinical significance of XRCC1 and LIG1 protein co-expression in human ovarian cancers." (PMID 34373746, 2021). "The data concurs with the platinum sensitization observed in LIG1 depleted ovarian cancer cells." (PMID 34373746, 2021). "We observed that cisplatin treatment increased LIG1 protein levels in ovarian cancer cells." (PMID 34373746, 2021). "We proceeded to pre-clinical evaluation of LIG1 in ovarian cancer cells." (PMID 34373746, 2021). "However, the detailed molecular mechanisms of the role of LIG1 in ovarian cancer DNA repair are an area of ongoing investigation and as such are a limitation of the current study." (PMID 34373746, 2021). "The data suggests LIG1 may influence platinum sensitivity and is induced after platinum therapy in ovarian cancer cells." (PMID 34373746, 2021). "In ovarian cancer cell lines, LIG1 depletion increased platinum cytotoxicity." (PMID 34373746, 2021). "Pre-clinically, platinum sensitivity was investigated in LIG1 depleted ovarian cancer cells." (PMID 34373746, 2021). "Therefore, we first tested LIG3 levels in LIG1 depleted ovarian cancer cells." (PMID 34373746, 2021). "Given the key roles played by LIG1, LIG3 and LIG4 in genomic integrity 8 and the response of cancer cells to therapy, we investigated their role in ovarian cancer pathology and potential as novel therapeutic targets." (PMID 34373746, 2021). "LIG1 depletion promotes platinum sensitivity: We conducted pre-clinical studies of LIG1 in platinum sensitive (A2780, PEO1) and platinum resistant (A2780cis, PEO4) ovarian cancer cell lines." (PMID 34373746, 2021). "This is the first comprehensive study of LIG1, LIG3 and LIG4 in epithelial ovarian cancers." (PMID 34373746, 2021).
ovarian carcinoma (continued). "Whether LIG1, LIG3 and LIG4 can influence ovarian cancer pathogenesis and therapeutics is largely unknown." (PMID 34373746, 2021).
lymphopenia (3 papers, 2020 to 2024). Reduction in the number of lymphocytes. "Here we report a homozygous LIG1 mutation (p.A624T), affecting a universally conserved residue, in a patient presenting with leukopenia, neutropenia, lymphopenia, pan-hypogammaglobulinemia, and diminished in vitro response to mitogen stimulation." (PMID 38896336, 2024). "Their clinical manifestations include hypogammaglobulinemia, decreased B and T cell counts, and lymphopenia, suggesting that rapidly dividing adaptive immune cells are more sensitive to LIG1 perturbations." (PMID 38896336, 2024).
neuroblastoma (3 papers, 2019 to 2023). Neuroblastoma (NB) is the most common solid, extracranial childhood tumor. "Reduction in LIG3 and LIG1 expression levels in neuroblastoma cells led to DSB accumulation and cell death." (PMID 31737108, 2019). "Previous studies discovered that LIG1, LIG3, and PARP1 protein were upregulated in tumorigenic neuroblastoma cells." (PMID 33194676, 2020). "MMEJ machineries including DNA ligase III (LIG3), DNA ligase I (LIG1), and poly(ADP-ribose polymerase 1) (PARP1) are highly expressed in neural crest stem cells, the cell of origin for neuroblastoma, and thought to contribute to the tumor's ability to survive double-stranded break triggering events." (PMID 37457440, 2023). "Inhibition of LIG1 and LIG3 led to DSB accumulation and cell death in neuroblastoma, suggesting the alt-NHEJ pathway as a critical function in cancer cell survival and progression HDACI differentially acetylated DNA repair factors to inhibit NHEJ activity in cancer cells." (PMID 33194676, 2020).
bladder urothelial carcinoma (2 papers, 2020 to 2022). "Immunohistochemistry and online analyses validated the functions of 4 key immune-related genes (LIG1, TBX1, CTSG and CXCL12) in bladder urothelial carcinoma." (PMID 32579540, 2020).
Bloom syndrome (2 papers, 2022 to 2024). Bloom syndrome (BSyn) is a rare chromosomal breakage syndrome characterized by a marked genetic instability associated with pre- and postnatal growth retardation, facial sun-sensitive telangiectatic erythema, increased susceptibility to infections, and predisposition to cancer. "Many DNA repair defects are associated with chromosomal instability most commonly observed in FA, AT, Bloom syndrome, and Nijmegen breakage syndrome (NBS), but also in ATLD, ICF and NER syndromes, DNA ligase I (LIG1) deficiency, and DNA recombinase repair defects." (PMID 34716846, 2022).
cervical cancer (2 papers, 2022 to 2024). A primary or metastatic malignant neoplasm involving the cervix. "In this experiment, we found that TDG and LIG1 were expressed at high levels in cervical cancer, and OGG1 expression was low in cervical cancer (P < 0.05)." (PMID 35379200, 2022). "This research delved into the development of novel potential cancer drugs targeting class 1 histone deacetylases (HDACs) and highlights the promise of two specific ligands, LIG1 and LIG2, as potent HDAC inhibitors with potential applications in cervical cancer treatment." (PMID 38675404, 2024). "The expression levels of PCNA, TDG, and LIG1 were elevated in cervical cancer group compared with the normal and CIN groups (P < 0.05)." (PMID 35379200, 2022). "Few studies have examined LIG1, SMUG1, and TDG in CIN and cervical cancer." (PMID 35379200, 2022). "However, expression levels of TDG, LIG1 and OGG1 have not been examined in cervical cancer tissues." (PMID 35379200, 2022).
immunodeficiency 96 (2 papers, 2024 to 2026). "Biallelic hypomorphic variants of LIG1 cause immunodeficiency-96." (PMID 41895445, 2026).
melanoma (2 papers, 2018 to 2023). A malignant, usually aggressive tumor composed of atypical, neoplastic melanocytes. "Similarly, analysis of the melanoma TCGA dataset revealed that GREB1 gene expression was positively correlated with the expression of proliferative marker genes (CDK2, MYC, CCND1, and LIG1) and negatively correlated with CDKN1B." (PMID 37658191, 2023).
non-small cell lung carcinoma (2 papers, 2019 to 2020). A group of at least three distinct histological types of lung cancer, including non-small cell squamous cell carcinoma, adenocarcinoma, and large cell carcinoma. "A recent study has revealed that RNA-binding protein SRSF1 promote tumor cell proliferation and progression by increasing LIG1 mRNA stability in non-small cell lung cancer." (PMID 32071816, 2020).
oligodendroglioma (2 papers, 2023). A well-differentiated (WHO grade II), diffusely infiltrating neuroglial tumor, typically located in the cerebral hemispheres. "We observe that different genes belonging to this pathway exhibit different trends, for example genes such as POLD1(chr19), RPA2(chr1), and LIG1(chr19) loose a copy in IDH-mut oligodendrogliomas, while genes RPA3(chr19), PMS2(chr19), PCNA(chr20) and POLD2(chr7) gain a copy in IDH-wt GBM." (PMID 36918656, 2023).
Omenn syndrome (2 papers, 2022). An inflammatory condition characterized by erythroderma, desquamation, alopecia, chronic diarrhea, failure to thrive, lymphadenopathy, and hepatosplenomegaly, associated with severe combined immunodeficiency (SCID). "For the first time Omenn syndrome is described in a compound heterozygote carrying two the novel variants p.Arg771Gly and p.Pro260* in the LIG1 gene." (PMID 36341401, 2022).